CDK1 (cyclin dependent kinase 1)
Diseases named in the same sentence as CDK1 in open-access papers (continued):
Sharing a sentence is not in itself a finding about the gene and the disease.
tumor (continued). "One potential therapeutic avenue for improving the lysis of brachyury-high tumor cells consists of tumor pretreatment with an inhibitor of the G2 checkpoint kinase, WEE1, which normally suppresses the activity of CDK1 via phosphorylation on Tyr-15." (PMID 29774202, 2018). "In contrast to CDK1 knockdown, transfection of RCC cell lines with either si-RNASEH2A or si-CD151 resulted in impaired tumor proliferation." (PMID 29843367, 2018). "Inhibition of CDK1 activity can successfully suppress the in vitro and in vivo tumor growth of PAAD, further proving the pivotal role of CDK1 pathway in PAAD progression." (PMID 29903985, 2018). "CDK1 also stimulates the enzymatic activity of SIRT3, which enhances mitochondrial function and tumor radioresistance." (PMID 28434945, 2017). "Bcl2, VEGFA, PTEN, Jun, Fos, APC2 were up-regulated and Ccna2, Cdc25a, Mcm3, Mcm6, Ccnb2, Mcm5, Cdk1, Gadd45a, Myc were down-regulated in MMQ tumor stem-like cells group." (PMID 28163656, 2017). "In the pathway in cell cycle, we found that the expression of Ccna2, Cdc25a, Mcm3, Mcm6, Ccnb2, Mcm5, Cdk1, Gadd45a were down-regulated in the MMQ tumor stem-like cells." (PMID 28163656, 2017). "We found that the expression levels of CDK1, HDAC2 and RAD21 were increased in tumor tissues compared with the adjacent normal tissues." (PMID 28434945, 2017). "CDK1 and MAD2L1 were selected for further study due to their known role in regulating tumor cell cycle and mitosis." (PMID 27835911, 2016). "In this particular case, MYC overexpressing tumour cells appear to be reliant upon the activity of the inhibitor of apoptosis protein (IAP), BIRC5 (survivin) a CDK1 target." (PMID 26881434, 2016). "As for the relation to the clinical stage of OSCC, the incidence of CDK1 expression increases along with the progression of tumor stage until stage III, but it decreases in notable advanced tumor, stage IV." (PMID 25129248, 2015). "Analysis of E2F2, CDK1, CDC20, UBE2C and the proliferation biomarker Ki67 in xenograft sections showed consistently lower levels in the shASCT2 tumours." (PMID 25693838, 2015). "Nevertheless, both cdk1 expression and CCNB1 expression were significantly higher in MYCN-amplified tumor." (PMID 26029996, 2015). "As expected, there was a down regulation of cellular proliferation molecules CDK1, CDK2, CDK4, CDK6, Cyclin D1, Cyclin E and Cyclin B1 and upregulation of p16 and p21 in the xenograft tumor tissues by IHC." (PMID 26590805, 2015). "Meriolin 3 prevents phosphorylation of CDK1, CDK4 and CDK9 sites, and potently inhibits tumour growth in mouse xenograft models." (PMID 25625291, 2015). "Our result is consistent to previous report showing that CDK1 is overexpressed in HCC and its expression is correlated with aggressive tumor behavior and recurrence of HCC." (PMID 26536659, 2015). "In a xenograft mouse model, the authors found that 6-OHD significantly decreased tumor growth and the volume and weight of HCT-116 xenografts by suppressing cyclin-dependent kinase 1 and 2 (CDK1 and CDK2) activity in tumors." (PMID 24705463, 2014). "Very few tumor samples (4 cases) express nuclear but not cytoplasmic CDK1, suggesting that loss of proteins such as 14-3-3σ that sequester CDK1 in the cytoplasm might contribute to this finding, but loss or reduction of 14-3-3σ is very rare in primary NSCLC specimens." (PMID 21887332, 2011). "We have provided the first demonstration that protein expression of the novel CDK1 activator, RGC-32, is upregulated in cells immortalized by a human tumour virus, further supporting a role for deregulated RGC-32 expression in tumour development." (PMID 22163048, 2011). "We next explored whether CDK1 may phosphorylate USP33 and affect its tumor-promoting function in PDAC cells." (PMID 40695806, 2025).
tumor (continued). "This study demonstrated that AS/BJO-NEs inhibited the proliferation, migration, invasion and EMT process of OSCC by down-regulating CDK1 and subsequently reducing MTFR2 expression, exerting anti-tumor effects and providing new possibilities and a theoretical foundation for OSCC treatment." (PMID 40748969, 2025). "Kinase–substrate enrichment analysis (KSEA) further illustrated the activation of CDK1/2, which played a central role in cell cycle regulation, in the high-TMB group, hinting at abnormal up-regulation of tumor proliferation and therapeutic potential of CDK inhibitors." (PMID 40917497, 2025). "Notably, both RNA-seq and RT-qPCR analyses consistently demonstrated significant downregulation of CDK1 mRNA expression following PAB treatment, which strongly suggests that CDK1 plays a crucial role in mediating PAB’s anti-tumor effects." (PMID 41142571, 2025). "Targeted knockout of DMT1 inhibits iron uptake by colon epithelial cells, disrupts the iron-regulated signaling pathway mediated by CDK1, JAK1 and STAT3, and consequently suppresses tumor cell proliferation in colon cancer mouse models, thereby reducing tumor burden." (PMID 40144390, 2025). "Molecular docking analysis confirmed that API binds strongly to CDK1, and further experiments demonstrated that API suppresses NiNP-induced tumor growth both in laboratory cell models and in living organisms, while also blocking the activity of the CDK1/STAT3/FASN axis." (PMID 41226659, 2025). "Moreover, AS/BJO-NEs can inhibit this series of processes by suppressing the expression of CDK1 and regulating MTFR2, thereby inhibiting the onset and progression of neoplasms, and modulating the tumor microenvironment and inflammatory environment." (PMID 40748969, 2025). "Research shows that activation of the CHK1/CDK1 signaling pathway leads to NSCLC cell cycle arrest, thereby enhancing DDR capacity, attenuating cisplatin (DDP) cytotoxicity, and ultimately resulting in tumor cell resistance." (PMID 41473689, 2025). "First, pharmacological inhibition of CDK1 could potentially restore KDM6A’s nuclear localization and tumor suppressive function." (PMID 41184251, 2025). "Eight downregulated and two upregulated hub genes (CDK1 and KIF11) in the tumor were identified." (PMID 40457491, 2025). "There are many studies reporting on the mechanisms for lycorine to inhibit tumor cell growth and induce apoptosis, which involve target molecules such as MEK2, ROCK1, and miR-186/CDK1; however, it remains unclear which molecule has the main role." (PMID 38434975, 2024). "Conversely, downregulation of CCNB1, which reduces CDK1/CCNB1 activity, could inhibit the aggressive proliferation of tumor cells." (PMID 39795587, 2024). "This study compared the expression levels of miR-4516, Wnt 8B, FZD2, DVL3, FOSL1, CDK1, CDK2, CCNA1, and CCNB1 in primary LUAD tumor tissue with those in normal lung tissue using data from The Cancer Genome Atlas (TCGA) database to assess the consistency of our findings with the human sample." (PMID 38930863, 2024). "Furthermore, ccRCC tumours have higher levels of HNRNPD, lower levels of circCDK1, and higher levels of CDK1 mRNA and protein." (PMID 39180763, 2024). "Silencing CDCA8 could suppresses tumor growth, proliferation, and stemness of HCC by inactivating AKT/β–Catenin Signaling, and regulating the CDK1/cyclin B1 signaling axis." (PMID 38742112, 2024). "In addition, we found that the premature M-phase entry in tumour cells after SHCBP1 knockdown was due to WEE1 kinase downregulation, which resulted in decreased CDK1 phosphorylation at the Tyr15 residue." (PMID 38365687, 2024).
tumor (continued). "Highly expressed cyclin B1, even in the G1 phase, binds to its partner Cdk1, which phosphorylates a number of substrates regardless of the phase of the cell cycle and contributes to aggressive proliferation in tumor tissues." (PMID 37759511, 2023). "Moreover, the expression levels of BUB1, BUB1B, CDK1, CCNA2, MCM10 were significantly higher in CRC tumor tissues compared with normal tissues based on the GEPIA database." (PMID 37466419, 2023). "In addition, T-loop phosphorylation of CDK1/CDK2 was additively decreased by CT7001 and enzalutamide treatments, and a decrease in PolII phosphorylation was detected in tumours treated with CT7001 alone or in combination with enzalutamide." (PMID 37076563, 2023). "Using previously identified iron‐interacting proteins to compare the individual genes in these two pathways, we noticed that the gene expression of cyclin dependent kinase 1 (CDK1) and POLD1 were decreased 4.02‐ and 4.31‐fold by DFO in tumor colonoids, respectively." (PMID 36703617, 2023). "Taken together, our findings reveal the previous unrecognized tumor-promoting function of CDK1/PIN1 axis through destabilizing pVHL and provide the preclinical evidence that targeting CDK1/PIN1 is an appealing strategy in the treatment of multiple cancers with wild-type VHL." (PMID 36813923, 2023). "Correlation analysis using PDAC data from GEPIA database demonstrated that CDK1 expression in PDAC tumor tissue was higher than that in non-tumor tissue, while high levels of CDK1 were associated with poor overall survival or disease-free survival." (PMID 37743465, 2023). "who could show that ZIC5 is highly upregulated in NSCLC tumor tissues, and they suggested that ZIC5 may act as an oncogene by influencing CCNB1 and CDK1 complex expression." (PMID 37228492, 2023). "CDK1 is upregulated in patients with LUAD and accelerates tumor progression." (PMID 37265472, 2023). "Thus, there was a close relationship between the tumor immune microenvironment and this prognostic signature based on TAK1, CDK1, and SHARPIN." (PMID 37313428, 2023). "In BRCA, KIAA1429 promotes tumor progression by upregulating CDK1 expression, independent of m6A methylation." (PMID 37606975, 2023). "Moreover, CDK1 expression is positively correlated with the expression of the stemness marker SOX2, indicating a direct action on tumor maintenance and chemoresistance." (PMID 36839989, 2023). "These putative positive correlations show that a high CDK1/PBK/CHEK1 expression promotes tumor growth, aggressiveness, and immune evasion through the increased recruitment of T Cells CD4+ Th2, MDSCs, and TAM-M2, all of which have pro-tumor effects." (PMID 38003585, 2023). "Knocking down CDK1, CDK2, and Cyclin A significantly reduced the tumor cell number (right)." (PMID 37835543, 2023). "These negative modulators are usually tumor suppressors that inhibit CDK1 activation in tumor progression." (PMID 37311884, 2023). "Following that, the top 100 correlated proteins with CEP55 were collected from the GEPIA2 database, where the proteins KIF11, MK167, CDK1, PLK1, and CCNA2 represented the top 5 proteins correlated with CEP55 in the tumor microenvironment that influence immune cells in TME." (PMID 37175004, 2023). "Furthermore, we demonstrated that both CDK1 and STAT3 were highly expressed in tumor spheres from PANC-1 cells." (PMID 37743465, 2023). "In addition, as a potential tumor suppressor gene, C2orf40 inhibits the expression levels of cell cycle-related proteins (CCNE1 and CDK1), and blocks the cell cycle in G2/M phase." (PMID 35676661, 2022). "In addition, CDK1, CCNB1, and KIAA0101 were found to be substantially overexpressed in CCA, which can promote the proliferation of tumor cells." (PMID 36224755, 2022).
tumor (continued). "Pro-tumorigenic tumors displayed upregulation of genes related to pro-tumoral processes such as adhesion or migration (NCAM1), proliferation (CDK1, TOP2A) or extensively described tumor markers (CDKN2A, MTOR), among others, while showing an impairment in immune-related functions." (PMID 35329826, 2022). "Moreover, IHC staining performed on tumor sections from xenografts showed that ZNF655 and CDK1 expression level was markedly reduced in the ZNF655 knockdown group compared with the control group." (PMID 35927248, 2022). "The expression of these ten target genes was significantly upregulated in the tumor tissues compared to the adjacent normal tissues, and three of them (PLK1, CDK1, TOP2A) were also marked as landmark genes in CMap, which means these genes were widely expressed across the lineage." (PMID 35326724, 2022). "Overall, CCNB1, CDK1, and PAICS could be three critical genes that influence tumor stage development of NSCLC and they could produce a poor prognosis." (PMID 36081668, 2022). "Previous research also indicated that increasing STIL could promote CDK1/CCNB1 activity and indirectly participate in CCNB1 dependent proliferation in tumor cells." (PMID 35155425, 2022). "CDK1, PITX2, PRKAA2, and SFN were all upregulated in the tumor tissue of clinical samples." (PMID 35592706, 2022). "To further test the role of the CDK1-dependent cell cycle pathway, we analyzed the role of Forkhead Box O1 (FOXO1), which has been shown to have a direct link downstream of CDK1 and is involved in cell death, repair of DNA damage and tumor suppression." (PMID 35132135, 2022). "CDK1, HMMR, PTTG1, and TTK were positively correlated with tumor-infiltrate lymphocytes, which might involve tumor immune response." (PMID 34187556, 2021). "At the end of tumor evolution, MKI67, TOP2A, and CDK1 genes began to express." (PMID 34397824, 2021). "The expression of JUN, CDK1, IRF1, and STAT1 was significantly higher in the RSI-Low tumours." (PMID 34078917, 2021). "And the content of cell cycle-related proteins (CDK1, cyclin B1 and cyclinD1) in LINC01559-silenced H1299 cells was also significantly reduced, indicating that knockdown of LINC01559 blocked the cycle of tumor cells." (PMID 34823534, 2021). "The qRT-PCR results showed that CCNB1, CDK1, and RRM2 were significantly upregulated in liver cancer tumor samples (P < 0.0001) and cell lines (P < 0.05) compared with the relevant adjacent non-tumor liver tissues and normal liver cell LO2." (PMID 33685467, 2021). "Moreover, the cell cycle is an essential factor of cell growth; the cell cycle is regulated by complexes of cyclins and cyclin-dependent kinases during cell division, Cyclin D1, CDK1, CDK2, and CDK4 are often upregulated in tumor cells." (PMID 33953676, 2021). "CDK1 and STK26 were found to be the most upregulated in tumor-polarized myeloid cells." (PMID 34208043, 2021). "Additionally, the TOP2A, RRM2, NEK2, CDK1, and CCNB1 proteins were overexpressed in tumor liver tissues as compared to normal liver tissues according to the Human Protein Atlas database and previous studies." (PMID 34681056, 2021). "Furthermore, patients with high levels of CDK1 and WEE1 exhibit more aggressive TNBC tumours (classified as grade 3)." (PMID 34646365, 2021). "Based on downstream analysis, 5 hub genes, including CDK1, CDC20, CCNB1, CENPF, and MAD2L1, that could play a critical role in the early diagnosis, tumour stage, and poor outcomes of HBV-HCC were identified." (PMID 34603487, 2021). "Whether and how CDK1 mediates HCC progression remains unknown; therefore, further studies are imperative for determining the role of CDK1 in tumor progression." (PMID 34844614, 2021).
tumor (continued). "Isorhamnetin, kaempferol, FA, calycosin, hederagenin might play an anti-tumor role through targeting AKT1, CDK1 TYMS, MAPK3, AR, respectively." (PMID 34955857, 2021). "Collectively, CCNA2, CDK1, and CDC20 may serve as promising biomarkers for HB and provide prospects for designing targeted therapies using synthetic inhibitors as anti-tumor agents." (PMID 33718368, 2021). "In addition, a network of EZH2 and its interacting proteins (UBC, CDK1, HDAC1, SUZ12, EED) was found to participate in miR-26a-mediated tumor progression." (PMID 34381816, 2021). "At present, only RRM2, CDK1 and CCNA2 were identified as tumor therapeutic targets." (PMID 33083112, 2020). "Next, we investigated whether CDK1 and TFCP2L1 affected stemness features of BC cells by examining tumor sphere‐forming and clonogenic capacities." (PMID 31709755, 2020). "CDK1 and BUB1 have been proved to influence tumor progression by inducing cell cycle dysregulation." (PMID 32411535, 2020). "No expression of CDK1 was observed in normal tissues, while medium CDK1 gene expression was appreciated in tumor tissues." (PMID 32546690, 2020). "Roniciclib binds to and inhibits the activity of CDK1/Cyclin B, CDK2/Cyclin E, CDK4/Cyclin D1, CDK6/Cyclin D3, and CDK9/Cyclin T1, which are serine/threonine kinases playing key roles in the regulation of tumor cell proliferation and survival." (PMID 32737364, 2020). "Analyzing the expression and function of CDK1 and AURKB, the selected compounds could block cell proliferation and inhibit the growth of tumor." (PMID 32194417, 2020). "Meanwhile, ZNF300 might activate CDK1 through inhibition of WEE1 and MYT1 and modulation of the MYC/AURKA/BORA/PLK1 axis to promote the tumour cells to overcome G2 arrest and enter the M phase to avoid the apoptosis induced by chemotherapeutic drugs." (PMID 33078469, 2020). "Portrayed by this difference, modulating CDK1 activity altered tumor initiating potential without affecting cell proliferation in 2D assays." (PMID 31080551, 2019). "In addition, differential analysis from the ONCOMINE online database of tumor and normal tissue in two cohorts indicated that ZWINT, PRC1, CDKN3, CDK1 and CCNA2 were highly expressed in ACC samples." (PMID 31572440, 2019). "We analyzed differential phosphopeptide abundance between 80 tumor/NAT paired tissues to stratify phospho-substrates corresponding to different kinases and their inhibitors, and identified CDK1 and MAPK1 (ERK2) as two highly ranked phospho-substrate events in most tumors." (PMID 31675502, 2019). "As CDK1 activity is essential for the formation of BRCA-1 foci, its inhibition, combined with PARP inhibition, could effectively reduce BRCA-proficient tumor growth and regression." (PMID 30931929, 2019). "CDK1 interacts with apoptin during HCC tumorigenesis, and their link may play a role in mediating tumor cell apoptosis." (PMID 30705088, 2019). "Interestingly, TCGA data analysis revealed that the CDK1, CDK2, CCNB2, and SKP2 genes were significantly upregulated, but the SKP1 gene was downregulated in tumor samples compared with normal samples." (PMID 31717435, 2019). "MP-HX downregulated the expression of genes that could promote anti-apoptotic effect, cell cycle progression, tumor development and progression, which include BIRC5, CCNA2, CCNB1, CCNB2, CCNE2, CDK1/2/6, GINS2, HELLS, MCM2/10 PLK1, RRM2 and SKP2." (PMID 30042885, 2018). "To study the interactions among RNASEH2A, CDK1, and CD151 and their impact on tumor proliferation, we performed si-RNA knockdown studies on three ccRCC cell lines (786O, A704, KMRC3, all with VHL mutation) and one kidney urothelial carcinoma cell line (BFTC909, without VHL mutation)." (PMID 29843367, 2018).